LAMB3 (laminin subunit beta 3)
Description:
Binding to cells via a high affinity receptor, laminin is thought to mediate the attachment, migration and organization of cells into tissues during embryonic development by interacting with other extracellular matrix components.
Synonyms: LAMNB1; nicein-125kDa; kalinin-140kDa; BM600-125kDa; AI1A; JEB1A; JEB1B; LAM5
Tractability: Antibody: its Gene Ontology location is reachable by antibodies, with high confidence; UniProt places it where antibodies can reach, with medium confidence; UniProt predicts a signal peptide or a membrane-spanning region. PROTAC: ubiquitination databases record sites on it; its protein half-life has been measured. Other modalities: an approved drug acts on it.
Gene: Protein-coding gene on chromosome 1 (209,614,870 to 209,653,106, reverse strand). Ensembl gene ENSG00000196878.
Subcellular location: Secreted, extracellular space, extracellular matrix, basement membrane
Subcellular location (Human Protein Atlas): Vesicles; Predicted to be secreted
Pathways (Reactome):
Extracellular matrix organization: Anchoring fibril formation; Assembly of collagen fibrils and other multimeric structures; Degradation of the extracellular matrix; Formation of the dystrophin-glycoprotein complex (DGC); Laminin interactions; Non-integrin membrane-ECM interactions
Cell-Cell communication: Type I hemidesmosome assembly
Developmental Biology: Developmental Lineage of Pancreatic Ductal Cells
Disease: Attachment of bacteria to epithelial cells
Signal Transduction: MET activates PTK2 signaling
Gene Ontology:
Molecular function: protein binding; extracellular matrix structural constituent; structural molecule activity
Biological process: endodermal cell differentiation; epidermis development; substrate adhesion-dependent cell spreading; cell differentiation
Cellular component: extracellular matrix; basement membrane; extracellular region; laminin-5 complex; laminin-5B complex
Genetic constraint (gnomAD): Loss-of-function variants: 98 observed, 139.89 expected, observed/expected ratio (o/e) 0.7, 90% interval 0.59 to 0.83. The upper end of that interval is the gene's LOEUF score, 0.83, which puts it in group 3 of 6, group 1 being the genes least tolerant of losing a copy. Missense variants: 1,526 observed, 1,624.1 expected, observed/expected ratio (o/e) 0.94, 90% interval 0.9 to 0.98. Synonymous variants: 591 observed, 627.37 expected, observed/expected ratio (o/e) 0.94, 90% interval 0.88 to 1.01.
Homologues: Orthologues: chimpanzee LAMB3 (98% identical), macaque LAMB3 (96% identical), dog LAMB3 (85% identical), pig LAMB3 (83% identical), rat Lamb3 (83% identical), guinea pig LAMB3 (82% identical), mouse Lamb3 (82% identical), rabbit LAMB3 (82% identical), tropical clawed frog lamb3 (49% identical). Paralogues in human: LAMB2 (34% identical), LAMB1 (33% identical), LAMB4 (32% identical), LAMA5 (22% identical), LAMA3 (21% identical), USH2A (21% identical), LAMA1 (21% identical), LAMA2 (21% identical), LAMC1 (20% identical), LAMC3 (19% identical), AGRN (17% identical), HSPG2 (15% identical), and 15 more.
Diseases named in the same sentence as LAMB3 in open-access papers:
LAMB3 is named in the same sentence as 92 diseases in open-access papers, as found by Europe PMC text mining. Sharing a sentence is not in itself a finding about the gene and the disease. The quoted sentences say what the papers report.
pancreatic cancer (24 papers, 2016 to 2025). "This particular subset exhibited elevated expression of COL17A1 (collagen type XVII alpha 1 chain), LAMB3 (laminin subunit beta-3) and other genes associated with tumor progression and worse prognosis in pancreatic cancer." (PMID 40092486, 2025). "It has also been shown that LAMB3 is associated with diagnosis, prognosis, and the immune microenvironment in pancreatic cancer." (PMID 37577750, 2023). "Similarly, Laminin subunit beta-3 (LAMB3) encoding the β3 subunit of laminin-332, participating in the invasion and metastasis of colon cancer, pancreatic cancer, and prostate cancer." (PMID 37469408, 2023). "The role of laminin subunit beta-3 (LAMB3) has been studied extensively in several cancers, for example, pancreatic cancer, head and neck squamous cell carcinoma, thyroid cancer, and colorectal cancer." (PMID 38473784, 2024). "LAMB3 gene is considered a pro-metastatic gene in various cancers such as lung cancer, gastric cancer, pancreatic cancer, colorectal cancer and papillary thyroid cancer." (PMID 38473784, 2024). "Recent studies described that upregulated LAMB3 activated AKT in pancreatic cancer, thyroid cancer and CRC." (PMID 35992840, 2022). "The expression level of laminin β3 (LAMB3) were upregulated in the ECM of many tissues including pancreatic cancer, lung cancer, colon cancer." (PMID 36167975, 2022). "The laminin subunit beta-3 (LAMB3) is an oncogenic factor capable of enhancing the proliferation and migration of pancreatic cancer cells via stimulation of PI3K/Akt signaling pathway." (PMID 32503307, 2020). "A recent study of LAMB3 upregulation implicates this gene in cell apoptotic, proliferating and metastatic events in patients that suffer from pancreatic cancer." (PMID 33256133, 2020). "In the promoter levels of Cav1, Met, Mylpf, and Lamb3, which were all survival significant factors in pancreatic cancer, TF Rreb1 was discovered to be in the minor view." (PMID 32266133, 2020). "In pancreatic cancer, LAMB3 plays important roles in cell cycle arrest, apoptosis, proliferation, and invasion by regulating the PI3K/Akt signaling pathway." (PMID 32039003, 2019). "For the laminin subunits (LAMA3, LAMA4, LAMB3 and LAMC2) that were found to be associated with the prognosis of pancreatic cancer, we further analyzed their TCGA tumor tissue expression profiles." (PMID 31182680, 2019). "It is widely recognized that LAMB3 also plays important roles in the tumorigenesis and progression of thyroid cancer, papillary thyroid cancer, hepatocellular carcinoma, and pancreatic cancer." (PMID 32039003, 2019). "In the present study, we initially screened out four differentially expressed subunits (LAMA3, LAMA4, LAMB3 and LAMC2) of the laminin gene family that were found to be associated with the clinical outcome of pancreas cancer patients in TCGA." (PMID 31182680, 2019). "Taken together, these results suggest that LAMB3 is overexpressed in pancreatic cancer tissues and may be used as a prognostic indicator." (PMID 32039003, 2019). "It has been reported that LAMB3 may play a significant role in the prognosis and progression of pancreatic cancer." (PMID 30519576, 2018). "Moreover, LAMB3, another protein assigned to these pathways, has also been shown by a recent study to mediate apoptotic, proliferative, invasive, and metastatic behaviors in pancreatic cancer by regulating the PI3K/AKT signaling pathway." (PMID 33194391, 2020). "Laminin subunit β3 (LAMB3) promotes cell survival, invasion, and metastasis through the PI3K/Akt axis in patients with pancreatic cancer." (PMID 39511483, 2024). "In pancreatic cancer, miR-24-3p was reported to suppress the progression of PDAC by targeting LAMB3." (PMID 36114946, 2023). "LAMB3 has been shown to regulate the PI3K/Akt signaling system and promote apoptotic, proliferative, invasive, and metastatic characteristics in pancreatic cancer." (PMID 38028209, 2023).
pancreatic cancer (continued). "In pancreatic cancer, CMTM4, LAMB3, and IGF2BP2 all promote tumor proliferation, invasion, and metastasis through this activation pathway while inhibiting the cell cycle and apoptosis to play a carcinogenic role." (PMID 35783291, 2022). "THBS2 and VCAN were expressed in both stromal and pancreatic cancer cells, whereas ITGA2, LAMB3, and LAMC2 were solely expressed by pancreatic cancer cells." (PMID 34007003, 2021). "Oncomine analysis of cancer vs. normal tissue confirmed that COL12A1, FN1, ITGA2, LAMB3, LAMC2, THBS2, and VCAN were significantly overexpressed in pancreatic cancer from different datasets." (PMID 34007003, 2021). "The protein expression of hub genes was higher in pancreatic cancer tissue than in normal pancreatic tissue samples, wherein ITGA2, LAMB3, and LAMC2 were exclusively expressed in pancreatic cancer cells." (PMID 34007003, 2021). "Histopathological evidence shows that ITGA2, LAMB3, and LAMC2 are expressed exclusively from pancreatic cancer cells." (PMID 34007003, 2021). "Moreover, in the Pei pancreas dataset, COL12A1, FN1, ITGA2, LAMB3, LAMC2, THBS2, and VCAN mRNA expression levels were higher in pancreatic cancer tissue than in normal pancreatic tissue samples." (PMID 34007003, 2021). "Interestingly, a previous report confirmed that LAMB3 and LAMC2 were exclusively derived from pancreatic cancer cells." (PMID 34007003, 2021). "To determine whether the expression of LAMB3 correlated with the overall survival rates of PDAC, we further analyzed the clinical data of 176 pancreatic cancer patients from The Cancer Genome Atlas (TCGA)." (PMID 32039003, 2019). "LAMB3 is a potential biomarker of cancer invasion and metastasis that is involved in the focal adhesion pathway, but a role for LAMB3 in pancreatic cancer has not been investigated previously." (PMID 30850586, 2019). "LAMB3 has been reported to play a protumorigenic role in CRC through the AKT-FOXO3/4 axis.ERO1A has been reported to be an unfavorable factor in multiple cancers, including pancreatic cancer and breast cancer, with a cancer-promoting effect in HCT116 CRC cells by regulating integrin-β1." (PMID 36209225, 2022). "While LAMB3 is involved in the invasive and metastatic abilities of some types of cancer, including colon, pancreas, lung, cervix, stomach, and prostate cancer, its mechanism of action in pancreatic cancer has not been investigated previously." (PMID 30850586, 2019). "It was also observed that ITGA2, LAMB3, and LAMC2 were the only proteins expressed in pancreatic cancer cells but not in stromal cells." (PMID 34007003, 2021).
breast carcinoma (18 papers, 2009 to 2024). "Within our list of 61 upregulated male versus female breast cancer genes linked to cancer-specific enhancers, we identified at least two super-enhancers; one linked to LAMB3 and the other to CD47." (PMID 37685859, 2023). "LAMB3 has been previously related with focal adhesion for cell migration in breast cancer, and its higher expression is associated with worse overall survival (OS) and disease-free survival (DFS) in pancreatic ductal adenocarcinoma (PDAC)." (PMID 37685859, 2023). "PROM1 and LAMB3 showed lower protein levels in HIV-negative breast cancer tissues compared in those found in HIV-positive breast cancer tissues." (PMID 33194615, 2020). "Lamb3 is the beta chain for laminin 5, which has been shown to promote migration of breast cancer cells." (PMID 23484019, 2013). "The expression of CTNNAL1 and LAMB3 inversely correlated with ZNF750 expression in breast cancer." (PMID 35879327, 2022). "They showed that zinc-finger protein 750 (ZNF750) is a negative regulator of the migration, and invasion of breast cancer cells by repressing a prometastatic transcriptional program, which includes genes involved in focal adhesion and extracellular matrix interactions, such as LAMB3 and CTNNAL1." (PMID 35879327, 2022). "We highlight two examples of previously unannotated cancer-cell-specific enhancers of ANXA2 and PRDX4 gene expression and show evidence for super-enhancer regulation of LAMB3 and CD47 in male breast cancer cells." (PMID 37685859, 2023). "In keeping, we showed that ZNF750 negatively regulates cell migration and invasion in breast cancer cells; in particular, ZNF750 binds and recruits KDM1A and HDAC1 on the LAMB3 and CTNNAL1 promoters." (PMID 33298895, 2020). "To biologically validate these findings, we performed IHC assay to detect the expression of four proteins (PROM1, LAMB3, SLC6A4, and MRPS12) generated from those genes found to be differentially expressed in HIV-positive breast cancer samples." (PMID 33194615, 2020). "Further, we determined a significant overlap of the pathways characterizing PRA transgenics and those in breast cancer subtypes Luminal A and Luminal B and identified novel putative biomarkers, such as PDHB and LAMB3." (PMID 29940887, 2018). "HOTAIR increased breast cancer invasiveness and metastasis by inducing positive regulators of cancer metastasis (ABL2 SNAIL, LAMB3 and LAMC2) in a manner dependent on PRC2." (PMID 23936419, 2013). "In fact, we would like to speculate that besides repressing LAMB3 and CTNNAL1 expression, ZNF750 might also inhibit migration and invasion in breast cancer by repressing the expression of RAC1." (PMID 33298895, 2020). "Some genes associated with cell adhesion were analyzed from this radiation- and estrogen-induced experimental breast cancer model, including E-cadherin gene CDH1, DSC3, GJA1, the Integrin alpha 6 gene ITGA6, the Integrin beta 6 gene ITGB6, the Keratin genes KRT14, KRT16, KRT17, KRT6B, and LAMB3." (PMID 36293530, 2022). "We found that TGFβ stimulation increased the binding of ΔNp63 to LAMB3, ITGA2 and SERPINE1 loci in MCF10A MII cells and in HCC1954 breast cancer cells without affecting ΔNp63 mRNA expression." (PMID 39180088, 2024).
epidermolysis bullosa (16 papers, 2013 to 2025). Epidermolysis bullosa (EB) is a group of genetic skin diseases that cause the skin to blister very easily. "Junctional epidermolysis bullosa (JEB) is a subtype of epidermolysis bullosa caused by mutations in the LAMB3 gene." (PMID 40509691, 2025). "To explore this further we examined the translation of the mRNA encoding the extracellular matrix protein laminin β3 (LAMB3) since a LAMB3-PTC mutant is implicated in the blistering skin disease Epidermolysis bullosa (EB)." (PMID 23861776, 2013). "De Luca and his colleagues isolated epidermal keratinocyte stem cells from a patient who carries a null allele and a single point mutation in the LAMB3 gene encoding laminin beta 3 subunit, and thus is affected by junctional epidermolysis bullosa." (PMID 24406242, 2013). "Additionally, gentamicin-induced upregulation of LAMB3 has shown improved healing in junctional epidermolysis bullosa patients with nonsense mutations." (PMID 38709270, 2024). "A PTC mutant of LAMB3 has been implicated in the blistering skin disease Epidermolysis bullosa (EB)." (PMID 23861776, 2013). "Proof of bioactivity of RpL35 ligands in selective increase of full-length LAMB3 provides the basis for an alternative, targeted therapeutic route to replenish LAMB3 in severe junctional epidermolysis bullosa." (PMID 38282649, 2024). "Significantly enriched keywords associated with our group of genes were Epidermolysis bullosa due to four genes with variants in our study group (EXPH5, PLEC, COL7A1, LAMB3)." (PMID 36454308, 2023). "The clinical synopsis of LAMB3-related AR epidermolysis bullosa, junctional 1A intermediate includes enamel hypoplasia, enamel pitting and corneal erosion, corneal scarring besides skin, hair and nails defects." (PMID 37228816, 2023). "A case report of transgenic epidermal grafting for junctional epidermolysis bullosa (JEB) recently reported long-term outcomes for one patient with JEB who received grafts expressing full-length, corrected LAMB3, which encodes for laminin-332." (PMID 36253825, 2022). "Mutations of LAMA3, LAMB3, LAMC2, DST, and COL17A1 have been reported in heritable skin fragility disorders and epidermolysis bullosa (EB)." (PMID 36430582, 2022). "A 7-year-old boy suffering from epidermolysis bullosa underwent a series of autologous skin equivalent transplants consisting mainly of posttransduction keratinocytes (the retroviral vector with LAMB3 cDNA), transplanting almost the entire skin surface of the child (0.85 m2)." (PMID 39184355, 2024). "Each of the individuals reported in this publication (4.1, 4.2, 4.3, 4.4 and 4.5) carrying mutations in LAMB3 present with hypoplastic AI with an irregular pitted and thinner enamel and no sign of epidermolysis bullosa." (PMID 37228816, 2023). "Work on editing the keratinocytes of patients with epidermolysis bullosa began in the 1990s, aiming to form a stable cell line expressing a copy of the corrected COL17A1, LAMB3, ITGB4, K5, and K14 genes." (PMID 39184355, 2024). "Notably, LAMA3, LAMB3, and ITGB4 are involved in junctional epidermolysis bullosa." (PMID 37745851, 2023). "These same genes, under an autosomal recessive inheritance transmission are responsible for various forms of epidermolysis bullosa (EB: Non-Herlitz junctional epidermolysis bullosa (nH-JEB) COL17A1; recessive dystrophic epidermolysis bullosa (RDEB) COL7A1; junctional EB (JEB) LAMA3, LAMB3, LAMC2)." (PMID 37228816, 2023).
junctional epidermolysis bullosa (14 papers, 2013 to 2025). "When both alleles of LAMB3 are defective, it could cause junctional epidermolysis bullosa (JEB), while with only one mutant allele in the C-terminus of LAMB3, it could result in severe hypoplastic AI without skin fragility." (PMID 25769099, 2015). "Genetically corrected epidermal keratinocytes have been successfully applied to overcome the effects of LAMB3 mutations in junctional epidermolysis bullosa (JEB), a devastating skin disease." (PMID 35537467, 2022). "Recessive dystrophic epidermolysis bullosa (RDEB) and junctional epidermolysis bullosa (JEB) are severe blistering skin disorders caused by mutations in genes encoding type VII collagen (COL7A1) and laminin 332 (LAMA3, LAMB3, or LAMC2), respectively." (PMID 41210582, 2025). "Severe junctional epidermolysis bullosa is a rare genetic, postpartum lethal skin disease, predominantly caused by nonsense/premature termination codon (PTC) sequence variants in LAMB3 gene." (PMID 38282649, 2024). "Of note, the successful autologous stem cell therapy toward junctional epidermolysis bullosa (JEB) patients using epidermal stem cells after gene correction (retroviral transduction of LAMB3) needs to be highlighted." (PMID 37340491, 2023). "Mutations in both alleles of LAMA3, LAMB3, and LAMC2 can cause junctional epidermolysis bullosa (JEB)." (PMID 25769099, 2015). "Mutations in the VWA domains of type VI collagen result in Bethlem and Ulrich muscular dystrophies, while mutations in LAMB3 cause junctional epidermolysis bullosa (both Herlitz and non-Herlitz type)." (PMID 23956175, 2013). "More recently, CEAs have enabled epithelial gene therapy in patients with junctional epidermolysis bullosa (JEB), a blistering disease in which epithelia are inadequately anchored to the basement membrane owing to mutations in genes encoding laminin 332 (LAMA3, LAMB3, and LAMC2)." (PMID 29288165, 2018). "Similarly, junctional epidermolysis bullosa (JEB) results from mutations in the LAMA3, LAMB3, LAMC2, and COL17A1 genes, which lead to defects in the production of laminin 332, an important protein to help attach the epidermis to the dermis." (PMID 30783081, 2019). "Biallelic mutations in LAMA3, LAMB3, and LAMC2 cause junctional epidermolysis bullosa with severe enamel hypoplasia in humans, while single allelic defects in LAMA3 and LAMB3 cause localized enamel defects without skin fragility." (PMID 40362374, 2025).